GATA1 (GATA binding protein 1)
Diseases named in the same sentence as GATA1 in open-access papers (continued):
Sharing a sentence is not in itself a finding about the gene and the disease.
myeloma (1 paper, 2020). "Compared to the CD34+ cells from myeloma bone marrow, the expression of GATA1 in normal CD34+ slightly suppressed by the CCL3 treatment which also caused by pho-p38." (PMID 33239656, 2020). "Altogether, the data from our study showed that CCL3/CCR1/phos-p38 plays a pivotal role in erythropoiesis of myeloma HSPCs via downregulation of the transcription factor GATA1." (PMID 33239656, 2020). "Importantly, blocking the CCL3 signal with BX471 (an antagonist of CCR1) effectively restored the effect of CCL3 on the downregulation of the transcription factor GATA1 in CD34+ cells in the myeloma microenvironment." (PMID 33239656, 2020). "More importantly, the expression of transcription factors, such as GATA1 and KLF1, which govern erythrocyte differentiation, was significantly downregulated in CD34+ HSPCs from myeloma patients." (PMID 33239656, 2020). "We also found that the expression of the transcription factors GATA1 and KLF1 was significantly downregulated in the HSPCs of myeloma patients, especially after the cells were co-cultured with bone marrow plasma from myeloma patients." (PMID 33239656, 2020). "In particular, the expression of the master regulators of erythropoiesis, including GATA1 and KLF1, was obviously decreased in myeloma CD34+ cells (FC < − 2.0, p < 0.01)." (PMID 33239656, 2020). "Elevated CCL3 in the BM plasma of myeloma further inhibited the erythropoiesis of HSPCs via activation of CCL3/CCR1/p38 signalling and suppressed GATA1 expression." (PMID 33239656, 2020). "The master regulators of erythropoiesis, GATA1 and KLF1, were obviously downregulated in myeloma HSPCs." (PMID 33239656, 2020). "Real-time PCR and Western blotting further indicated the recovery of GATA1 expression at both the mRNA and protein levels after blocking the CCL3/CCR1/phos-p38 signalling pathway in CD34+ cells from myeloma patients." (PMID 33239656, 2020). "Interestingly, we found that a high level of CCL3 significantly suppressed GATA1 expression at both the mRNA and protein levels in CD34+ cells in myeloma bone marrow." (PMID 33239656, 2020).
non-small cell lung carcinoma (1 paper, 2022). A group of at least three distinct histological types of lung cancer, including non-small cell squamous cell carcinoma, adenocarcinoma, and large cell carcinoma. "It has been reported that GATA2-AS1 regulates GATA2 to impair non-small cell lung cancer cell proliferation via interacting with GATA1 protein at GATA2 promoter region and then blocks its transcription." (PMID 35752837, 2022).
Obesity (1 paper, 2023). Accumulation of substantial excess body fat. "WT and Gata1 KO mice had comparable degrees of obesity, SBP, and DBP." (PMID 37773694, 2023).
oral cancer (1 paper, 2025). "To further investigate the clinical relevance of KDM4C and GATA1, we conducted an immunohistochemical (IHC) analysis on 85 paraffin-embedded oral cancer specimens from Taipei Veterans General Hospital patients." (PMID 40259045, 2025).
oral lichen planus (1 paper, 2025). Oral lichen planus is a chronic inflammatory oral condition of unknown aetiology characterized by T-cell-mediated chronic immune response and abnormal epithelial keratinization cycle. "In a study on oral lichen planus, vitamin D has been shown to limit the activation of the STING signaling pathway by inhibiting the expression of GATA-1; this is consistent with our research." (PMID 40563965, 2025).
Oral squamous cell carcinoma (1 paper, 2024). "Recently, a pivotal study indicated that miR-876-3p antogomir, packaged and delivered by sEVs derived from CAFs, can target GATA-binding protein 1 (GATA1) and reduce cisplatin resistance in Oral squamous cell carcinoma (OSCC) cells." (PMID 39684264, 2024).
platelet disorders (1 paper, 2021). "Megakaryocytic differentiation is, therefore, dependent on the RUNX1/GATA1 balance as well, suggesting a likely mechanism by which these RUNX1-DBD mutants contribute to platelet disorders." (PMID 33397648, 2021).
primary myelofibrosis (1 paper, 2020). Myelofibrosis with myeloid metaplasia is a myeloproliferative disease with annual incidence of approximately 1 case per 100,000 individuals and age at diagnosis around 60 (an increased prevalence is noted in Ashkenazi Jews). "As the founding member of a family of transcription factors, Gata1 plays important roles in the development of erythroid and megakaryocyte lineages, and its insufficiencies is involved in primary myelofibrosis and other hematopoietic disorders." (PMID 33378745, 2020).
pulmonary fibrosis (1 paper, 2021). Chronic progressive interstitial lung disorder characterized by the replacement of the lung tissue by connective tissue, leading to progressive dyspnea, respiratory failure, or right heart failure. "Next, we evaluated pulmonary fibrosis in WT BALB/c and GATA1-/- mice in the single and re-infected groups." (PMID 34784389, 2021).
rheumatoid arthritis (1 paper, 2025). A chronic, systemic autoimmune disorder characterized by inflammation in the synovial membranes and articular surfaces. "GATA1 induces rheumatoid arthritis development by promoting the transcriptional activation of NOS2." (PMID 40650665, 2025).
selenium deficiency (1 paper, 2019). A nutritional deficiency disease resulting from inadequate selenium levels in the body, which can lead to impaired function of selenoproteins essential for antioxidant defense and thyroid hormone metabolism. "Selenium deficiency reduces the activity of the transcription factor GATA-1 (GATA-binding protein 1), responsible for erythroid differentiation, and compromises the transport of heme in the erythroblastic islands, damaging the terminal maturation of erythroblasts." (PMID 31540239, 2019).
Spherocytosis (1 paper, 2022). The presence of erythrocytes that are sphere-shaped. "Elevated HbF is a common finding in increased erythropoiesis as it occurs in spherocytosis and GATA1-mediated dyserythropoiesis." (PMID 36231035, 2022).
T-cell leukemia (1 paper, 2014). A malignant disease of the T-lymphocytes in the bone marrow, thymus, and/or blood. "GATA2 and GATA1 are implicated at many (up to 90%) of the TAL1-bound sites in normal hematopoietic cells, and GATA3 along with ETS1 and RUNX1 can direct TAL1 binding when it is aberrantly expressed in T-cell leukemias." (PMID 25319994, 2014).
Wilms tumor (1 paper, 2008). An embryonal neoplasm characterized by the presence of epithelial, mesenchymal, and blastema components. "Important for their relation to Wilm's Tumor, several of these TFs have previously been implicated in cancer (NANOG, GLI1, E2F1, POU5F1/OCT4, SPI-1, YY-1, GATA1, and C/EBP-β)." (PMID 18564415, 2008).
tumor (54 papers, 2008 to 2025). "The erythroid lineage markers expressed in multiple tumor and tumor-associated clusters were also reflected in spatial gene expression profiles, as indicated by the high levels of Alas2, Hba-a1 and Gata1 across tumor areas." (PMID 37414763, 2023). "Interestingly, after determining GATA1 as a high-risk gene, we have also found that the GATA1 expression is lower in the tumor tissue than the normal tissue." (PMID 36210802, 2022). "GATA1/SET7 expression positively associated with tumor size, nodal status and grade, and inversely correlated with the expression of estrogen receptor α (ERα), but they did not associate with age, progesterone receptor (PR) and human epidermal growth factor receptor 2 (HER2)." (PMID 26848522, 2016). "Kaplan-Meier survival analysis demonstrated that patients with high GATA1 expression exhibited significantly worse relapse-free survival compared to those with low GATA1 expression, reinforcing the role of GATA1 in tumor progression." (PMID 40259045, 2025). "This study investigates the role of KDM4C and its interaction with GATA1 in regulating heme metabolism and tumor progression in HNSCC." (PMID 40259045, 2025). "In order to investigate the correlation of GATA1 with clinical data, we separately analyzed the expression level of GATA1 in patients at the different ages and different tumor stages." (PMID 36210802, 2022). "GATA1 is an important transcription factor playing critical roles in hematopoiesis and tumor development 24-27." (PMID 35342335, 2022). "We further compared the GATA1 between the normal group and the tumor group, and found that the GATA1 expression was still high in the patients’ endometrial tissue of the normal group." (PMID 36210802, 2022). "SETD7 was needed for GATA-1-induced cell viability in vitro, and for tumour growth and angiogenesis in MDA-MB-231 xenografts." (PMID 35326563, 2022). "In the current study, we identified a novel role of GATA1 in tumor proliferation and gemcitabine resistance in PDAC." (PMID 31093285, 2019). "Mechanistically, cyclin D2, frequently thought to play a critical role in promoting tumor cell proliferation, was upregulated in GATA1 overexpressed cells." (PMID 31093285, 2019). "Upon the treatment of gemcitabine, we observed that GATA1 greatly counteracted gemcitabine-induced tumor shrink." (PMID 31093285, 2019). "A multivariate analysis revealed that tumor size, nodal status, grade, and GATA1 and SET7 status were independent poor prognostic factors of DFS and OS." (PMID 26848522, 2016). "After univariate analysis by Cox proportional hazards model, tumor size, nodal status, grade, and ER, GATA1, and SET7 status were demonstrated as significant prognostic parameters for disease-free survival (DFS) and overall survival (OS)." (PMID 26848522, 2016). "Meanwhile, we found the tumor malignancy of GATA1 S161A S187A cells was similar to control cells, only six of ten GATA1 S161A S187A mice underwent a liver metastatic phenotype, and one of ten mice exhibited lung metastasis." (PMID 25726523, 2015). "We hypothesize that the low level of GATA1 expression in tumor tissues may be related to the UCEC and some immune functions." (PMID 36210802, 2022). "By inhibiting GATA1 expression, mast cell maturation could be suppressed in the tumor tissue, thus treating cancer." (PMID 36210802, 2022). "Based on this, we speculate that GATA1 expression is high in UCEC tumor tissue while the survival decreases." (PMID 36210802, 2022). "RT-qPCR results suggested that the GATA1 expression was elevated in the collected tumor tissues versus the adjacent tissues (adjacent tissue vs. tumor: 2.14 vs. 4.80, p < 0.0001), which showed an inverse correlation with NRBP2 expression (r = −0.2674, p = 0.0241)." (PMID 35491849, 2022).
tumor (continued). "The results showed that the age, tumor stage and GATA1 could all exist as independent prognostic factors." (PMID 36210802, 2022). "These genes have been associated with tumour suppression (BRCA1 and FAT1), DNA repair (POLE), morphogenesis (HOXD11), epigenetic regulation (WHSC1), lipid metabolism (PPARG) and red blood cell development (GATA1)." (PMID 36131292, 2022). "TF GATA1 could positively regulate target gene PDCL3, which was modified by DNA methylation, to cause tumor cell proliferation and angiogenesis through signaling transduction protein PDK2." (PMID 31126066, 2019). "Here we show that a series of transcription factors, including C/EBPβ, GCM1, and GATA1, could act as potential modulators of histone methylation in tumor cells." (PMID 29712898, 2018). "SET7 knockdown abrogated the ability of GATA1 knockdown to repress MDA-MB-231 tumor growth." (PMID 26848522, 2016). "Again, the inhibitory effect of GATA1 knockdown on tumor growth could be rescued by GATA1 reexpression in the GATA1 knockdown cells." (PMID 26848522, 2016). "Eight weeks after injection, multiple tumor nodules were observed in the livers of GATA1 wt mice." (PMID 25726523, 2015). "ZNF268 may be similar to Egr1, which has been identified as a target of GATA-1 by ChIP-seq analysis and is regarded as a tumor repressor." (PMID 22235304, 2012). "Additionally, GATA1 is related to tumor chemotherapy resistance." (PMID 39695810, 2024). "Therefore, it is possible that GATA1 and the genes involved in RNA processing, including genes for RNA splicing, might have a cooperative tumor suppressive function." (PMID 36077026, 2022). "Besides, it may promote the apoptosis of mast cells by knocking out GATA1, thereby controlling tumor progression to some extent." (PMID 36210802, 2022). "Our study addresses this gap by examining how the interaction between KDM4C and GATA1 collaboratively regulates FECH expression, providing new insights into the molecular mechanisms linking heme metabolism to tumor growth and aggressiveness." (PMID 40259045, 2025). "It suggests that GATA1 is regulating the occurrence of ferroptosis in tumor-infiltrating CD8+ T cells, thus affecting the anti-tumor function to provide a new direction and theoretical basis for the study of ferroptosis in DLBCL with high GATA1 expression." (PMID 40391074, 2025). "To comprehensively assess tumor vessel functionality following autophagy inhibition, we used double-transgenic zebrafish (flk:GFP/Gata1:dsRED) and performed angiography using low-molecular-weight FITC-dextran (20 kDa)." (PMID 39744218, 2025). "Taken together, our outcome demonstrated the influence of GATA1/HSD17B6 regulatory axis in cisplatin resistance in LUAD, adding weight to the importance of therapeutic targets to enhancing tumor chemotherapy sensitivity." (PMID 39695810, 2024). "This study reports that GATA1- and HDAC2-mediated NRBP2 downregulation induced TME and angiogenesis in TC cells in vitro and tumor growth and macrophage infiltration in vivo." (PMID 35491849, 2022). "Among them, GATA1, RARA and LMO2 were lowly expressed, while E2F4 and CTBP2 were highly expressed in tumor parts." (PMID 35743687, 2022). "We conducted co-IP using transplanted tumor tissues and found that in the SENP1 down-regulated group, GATA1 binding affinity with SUMO1 was increased and GATA1 SUMOylation was enhanced as well." (PMID 35342335, 2022). "Our in vivo studies also indicated that reduction in SENP1 expression upregulated GATA1 SUMOylation, and thus resulted in decreased expression of CSN5 and ZEB1 in the tumor microenvironment, which decelerated TNBC progression and metastasis." (PMID 35342335, 2022). "In conclusion, this study reports that GATA1 can recruit HDAC2 to the NRBP2 promoter to induce its transcriptional suppression, which leads to M2 polarization of macrophages and tumor angiogenesis and development." (PMID 35491849, 2022).
tumor (continued). "Only two out of three lowly expressed TFs, namely GATA1 and LMO2, exhibited more than a two-fold change in tumor parts." (PMID 35743687, 2022). "Therefore, SETD7 could mediate GATA-1 tumour-promoting functions in BC." (PMID 35326563, 2022). "Otherwise, PDS increased the proportion of both hematopoietic stem cells and erythroid progenitor cells in the bone marrow, but inhibited spleen erythroid differentiation via inhibiting secretion of tumor EPO, GATA-1, and GATA-2." (PMID 32015754, 2020). "However, whether GATA1 regulates tumor angiogenesis is unclear." (PMID 26848522, 2016). "Furthermore, the concept that Spi-1 could inhibit the function of GATA-1 in erythroleukemic cells is supported by the reversal of tumorigenicity and the re-initiation of a differentiation program when GATA-1 expression is ectopically imposed in a Friend tumor cell line." (PMID 18983647, 2008). "Our data indicate that KDM4C and GATA1 cooperate to upregulate FECH, the terminal enzyme in heme biosynthesis, enhancing mitochondrial bioenergetics, oxidative phosphorylation, and supporting tumor aggression." (PMID 40259045, 2025). "Here we also demonstrate that mice lacking CTLs or T helper cells have higher tumor burdens, whereas the GATA1-/- group, lacking eosinophils, showed smaller average tumor volume but not significantly different to the WT group with complete immune cell context." (PMID 38524132, 2024). "We found that Epcam, Gpc3 and Dlk1 were highly expressed in a small percentage of cells ( < 25%) in tumor samples compared to normal control livers although not as remarkably as the erythroid genes (Gata1, Alas2, Rhd, Hba-a1)." (PMID 37414763, 2023). "Amh, marking immature Sertoli cells, was not detectable in our RNAseq dataset, while levels of mature Sertoli cells markers, Gata1 and Cldn11, were not different compared to WT, indicating the tumour cells had not acquired an immature Sertoli cell signature." (PMID 37564373, 2023). "In order to evaluate whether the GATA1 could exist as an independent prognostic factor, we performed univariate and multivariate COX regression analyses for its relation with the age and tumor stage, respectively." (PMID 36210802, 2022). "Considering the fine balance of the immune system, transgenic models of eosinophil modulation (such as GATA-1 knockout mice, IL5-/-, or IL5+/+ mice) or spontaneous tumor development would probably be more appropriate for this type of study, as well as the use of avatar mice." (PMID 34572273, 2021). "Moreover, an increased level of GATA1 was correlated to unfavorable LS and PFS in LC, especially the PFS in adenocarcinoma subtypes, and tumor stages." (PMID 34093794, 2021). "Importantly, the mechanistic biomarkers including JWA, p-p38, GATA-1, NEDD4, and SMURF1 were correspondingly changed in tumor tissues." (PMID 33875644, 2021). "3.3, we show the nodes having high role A and B motif centrality, such as HIFs, HDAC, BRCA1, EGR1, STAT1, GATA1 and GATA3, and also report their functions as master regulators in liver function, cell proliferation, tumor suppression and genomic stability, etc. as well as stress response." (PMID 32541819, 2020). "In this study, we identified GATA1 as a key regulator of VEGF expression and tumor angiogenesis." (PMID 26848522, 2016). "Thus, we tested the effects of GATA1 and SET7 on cancer cell proliferation in culture and tumor growth in a xenograft mouse model." (PMID 26848522, 2016). "Because of the important regulatory role for cell differentiation, it occurred to us whether GATA1 could regulate the proliferation of DLBCL or could regulate the proliferation and differentiation of tumor-infiltrating immune cells, which could affect the therapeutic effect of DLBCL." (PMID 40391074, 2025).
tumor (continued). "GATA2/5/6 expression changed noticeably throughout the tumor stages, according to correlation analysis of TCGA data using the Gene Expression Profiling Interactive Analysis (GEPIA) database, whereas GATA1/3/4 expression showed no discernible variations among tumor stages." (PMID 36961416, 2023). "Importantly, some RP genes (e.g., RPL5, RPL11 and RPS20) are known to be tumor-suppressor genes, which is not the case for GATA1." (PMID 35328001, 2022). "Notably, similar to tumor cells from diseased BCR-ABL transduced Cebpa−/− mice, the human erythroleukemia cell line K562 (established from a patient with CML in blast crisis) also expresses BCR-ABL and GATA1 and lacks C/EBPα." (PMID 33898929, 2021). "Furthermore, tumor cells expressed erythroid regulators such as SCL/TAL1 and GATA1." (PMID 33898929, 2021). "We speculate that miR-27a and miR-24 may serve at a ‘standby state’, which means they are ready for the manipulation by different cellular factors, as GATA-1 in erythropoiesis, c-MYC in tumour metastasis, Runx2 in osteoblast differentiation and PU.1 in B-cell development." (PMID 24049083, 2014). "The results indicated that the expression of GATA1, GATA4 and GATA6 remarkably varied across the tumor stages, whereas GATA2, GATA3 and GATA5 demonstrated no significantly changes in different tumor stages." (PMID 34093794, 2021).